RB1 (RB transcriptional corepressor 1)
Diseases named in the same sentence as RB1 in open-access papers (continued):
Sharing a sentence is not in itself a finding about the gene and the disease.
osteosarcoma (continued). "The clinical relevance of the RB1/E2F3a onco-spliceosome signature (REOSS) was demonstrated across various cancer types, with elevated expression observed in tumors exhibiting low RB1 and high E2F3a expression levels, which also correlated with poor prognosis in osteosarcoma (OS) patients." (PMID 38672640, 2024). "Furthermore, we found the downregulation of RB1 protein in osteosarcoma tissue and cryopreserved PDCs compared to hFOB1.19 and U2OS cells." (PMID 38744935, 2024). "Copy-number loss of RB1 was associated with lower immune scores in leiomyosarcoma but not in osteosarcoma and UPS." (PMID 37593416, 2023). "To address if DNA replication is a requirement for toxicity of PARP inhibition to unfold in RB1-defective osteosarcoma, we assessed whether preventing this process prevents PARPi-induced death." (PMID 34862364, 2021).
osteosarcoma (continued). "Our work documents that enforced RB1 loss causes clinically meaningful sensitivity (i.e. sensitivity akin to that seen in BRCA1,2-defective CAPAN1) in otherwise PARPi insensitive osteosarcoma lines, providing proof of concept for a direct role of RB1 loss in the selective PARPi sensitivity observed." (PMID 34862364, 2021). "In osteosarcoma, alterations in RB1 are identified in 29–47% of tumors." (PMID 33807947, 2021). "A significantly greater sensitivity of RB1-depleted CAL72 was also observed using niraparib, although with a smaller differential in median IC50 between groups (6–7-fold), consistent with observations comparing naturally RB1-defective and RB1-normal osteosarcoma lines." (PMID 34862364, 2021). "The loss or inactivation of RB1 function results in a significant 1.62-fold increase in mortality rates in patients with osteosarcoma compared with those in patients without this gene aberration." (PMID 33375764, 2020). "In sporadic (i.e., non-hereditary) cases of osteosarcoma, somatic mutations in the RB1 gene occur in 20–75% of tumors." (PMID 31130627, 2019). "For instance, rs77639117 T allele could increase the risk of osteosarcoma through upregulating miR-576, which in turn might downregulate RB1, a tumor suppressor gene inactivated in 35% of osteosarcoma patients." (PMID 30337581, 2018). "To assess the mechanism through which the RB-E2F pathway is being deregulated in the osteosarcoma cell lines without RB1 mutations, we analyzed CDK4 and CDK6 gene expression." (PMID 30220967, 2018). "CDK6 was also upregulated in the 3 osteosarcoma cell lines without RB1 mutations: 143B, SJSA-1 and U-2 OS." (PMID 30220967, 2018). "Since our work, another group has reported that RB1 alterations may serve as a prognostic marker for the management of osteosarcoma patients." (PMID 29056713, 2016). "As an example of this, we selected for validation one of the KGDs associated with RB1 mutation in osteosarcoma, DYRK1A (p = 6.8 × 10−3), a component of the DREAM complex previously identified as a protein interaction partner of RB1." (PMID 26947069, 2016). "Individual siRNAs designed to target a gene (as we have shown in the case of DYRK1A dependency in RB1 null cell lines) or small molecule inhibitors (as we have shown for the FGFR sensitivity of osteosarcoma cell lines) might be used as a form of validation." (PMID 26947069, 2016). "Because Pten deletion was insufficient to drive robust OS onset, we tested if co-deleting Rb1 and Pten could synergistically promote osteosarcoma formation." (PMID 26317218, 2015).
osteosarcoma (continued). "Notably, CDKN2A,MDM2, and RB1 also appeared in the PDK1-related gene signature derived from our correlation analysis, further supporting the association between PDK1 and osteosarcoma oncogenic programs." (PMID 40971960, 2025). "Previous studies showed that single deletion of Rb1 in mesenchymal cells and osteoblasts could not cause osteosarcoma formation." (PMID 35760773, 2022). "Thus, while the transcriptional regulation of UHRF1 is aberrant by means of RB/E2F pathway inactivation, RB1-wild-type osteosarcoma cells may preserve protein–protein interactions between RB and UHRF1." (PMID 36068209, 2022). "However, genomic or functional evidence for frank HRd is not detectable or significantly associated with RB1 loss in osteosarcoma." (PMID 34862364, 2021). "We coexpressed MmuPV1 E7 with plasmids expressing full-length RB1 (amino acid residues 1 to 928) or truncation mutants of RB1 lacking the amino terminus (amino acid residues 379 to 928) or the C terminus (amino acid residues 1 to 792) in SAOS2 human osteosarcoma cells." (PMID 34465025, 2021). "However, in osteosarcoma, loss of neither aE2F was sufficient to completely reverse the potentiation of the disease caused by Rb1 loss." (PMID 30220967, 2018). "Furthermore RB1 alterations are identified in 80% of primary sporadic osteosarcomas." (PMID 27074562, 2016). "Out of 56 identified recurrently amplified genes, 38 genes, such as TFEB and MYC, were found to be overlapping with pediatric OSA, while 69 genes, including RB1 and MSH3, were recurrently deleted in both human and canine osteosarcomas." (PMID 40507962, 2025). "Additionally, overexpressed miR-221 was shown to enhance cisplatin resistance in osteosarcoma via Protein phosphatase 2 (PP2A) targeting, but also rendered pancreatic cancer cells refractory to 5-FU through regulating the gene encoding for Retinoblastoma Protein 1 (RB1)." (PMID 32967267, 2020).
osteosarcoma (continued). "However, NGS revealed a complex genome lacking the characteristic EWSR1-associated rearrangements and instead identified deletions in RB1, PTCH1, and ATRX, confirming the diagnosis of osteosarcoma." (PMID 40115314, 2025). "We further assessed the response of PARPi in three different early-passage patient-derived models of metastatic osteosarcoma adapted for growth in 2D tissue culture, two of them positive for RB1 expression and one without detectable RB1." (PMID 34862364, 2021). "This analysis yielded scarHRD scores clearly lower than those detected for BRCA1,2-mutated cell lines for all osteosarcoma lines and absence of a significant difference between RB1-defective and RB1-normal osteosarcoma groups." (PMID 34862364, 2021). "Treatment with olaparib yielded a concentration-dependent increase in death-dye incorporation compared to vehicle-treated controls accompanied by widespread cytopathic effects in RB1-defective but not RB1-normal osteosarcoma lines." (PMID 34862364, 2021). "For example, CDKN2A is deleted in 22% of canines but only altered in 5% of human pediatric osteosarcomas, while RB1 is altered in 16% of human pediatric osteosarcomas but none of the canine tumors." (PMID 34344882, 2021). "Of the osteosarcoma cell lines examined in this study, SaOS-2 harbors a deletion in the RB1 gene that leads to a non-functional truncated protein, SJSA-1 has CDK4 amplification, and U-2 OS is p16 null." (PMID 30220967, 2018). "Furthermore, we identified identical aberrations which are frequently observed in osteosarcoma (e.g. amplification of Myc and LOH in RB1)." (PMID 25926029, 2015). "Co-deleting Rb1 with Pten greatly accelerated lipoma formation and increased the incidence to 100%, but did not induce osteosarcoma." (PMID 26317218, 2015).
osteosarcoma (continued). "Alterations like RB1 loss and MYC and VEGFA amplification may indicate a high risk of osteosarcoma, but none are yet validated for clinical risk stratification." (PMID 40563473, 2025). "The reasons for this discrepancy between the 45Ca and Osx p53Rb KO osteosarcoma models are not clear but could be related to Rb1 inactivation being a genetic driver of disease in the Osx p53Rb KO, but not in the 45Ca models." (PMID 37845394, 2023). "Luckily, RB1 and CDK4 mutations seem to be mutually exclusive in osteosarcomas and thus CDK4/6 inhibition may be applied without fear of reverting mutations, although they could occur as a response to multimodal chemotherapy." (PMID 33963544, 2021). "Therefore, it is not surprising that HELLS upregulation and overexpression in osteosarcoma is not restricted to RB1-null cases, but rather a generalized event observed across samples that bear RB-E2F pathway inactivation." (PMID 30220967, 2018). "Heterozygous Germline Rb1 disruption does not generate osteosarcoma with any detectably increased incidence, in stark contrast to humans heterozygous for germline RB ablation, who have a 500-fold increased incidence of osteosarcoma." (PMID 21403899, 2011). "To confirm these results were specific to RB loss and not the result of potential off-target effects of the RB-targeting shRNA, we also analyzed pRPA and DNA damage foci after siRNA-mediated depletion of RB and in RB1-null osteosarcoma cells." (PMID 37704395, 2023).